PDGFRB (platelet derived growth factor receptor beta)
Diseases named in the same sentence as PDGFRB in open-access papers (continued):
Sharing a sentence is not in itself a finding about the gene and the disease.
breast cancer (continued). "As models of EGFR+/PDGFRβ− cell lines, we used breast cancer BT-474 and epidermoid carcinoma A431 cell lines, which express moderate and high levels of EGFR, respectively, without expressing PDGFRβ, and are thus recognized by CL4 but not Gint4.T." (PMID 38532439, 2024). "PDGFRb was assessed by immunohistochemistry on tissue microarrays from 989 tumors of the SweBCG91RT trial, which enrolled lymph node-negative, stage I/IIA breast cancer patients randomized to RT after breast-conserving surgery." (PMID 33661437, 2021). "Furthermore, immunoblotting analysis showed that only two of the tested breast cancer cell lines (SUM159PT and Hs578T) exhibited marked accumulation of basal PDGFRβ levels and the majority of the cell lines expressed very low to none PDGFRβ levels." (PMID 30777101, 2019).
glioma (144 papers, 2007 to 2025). A benign or malignant brain and spinal cord tumor that arises from glial cells (astrocytes, oligodendrocytes, ependymal cells). "Glioma cells express PDGFRA, while PDGFRB is predominantly localized in the glioma-associated extracellular matrix." (PMID 37700840, 2023). "PDGFRβ is mostly restricted in the glioma-associated stroma, but can be induced in glioma cells by microglia to enhance the migration of glioma cells." (PMID 34470658, 2021). "PDGFRA and PDGFA have been shown to be expressed in tumour cells, whereas PDGFB and PDGFRB have been found in glioma-associated endothelial cells." (PMID 19707201, 2009). "Of note, in a previous study, using laser-capture microdissection and transcriptional analysis, the authors identified CD248 and PDGFRβ, both related to the pericyte phenotype, within upregulated molecules in glioma-associated vessels in comparison to normal vessels." (PMID 34272603, 2021). "Aptamers can specifically bind to proteins overexpressed in glioma cells, such as platelet-derived growth factor receptor β (PDGFRβ) and Axl receptor tyro-sine kinase, which are involved in the tumor growth and progression." (PMID 41473440, 2025). "Violin plots demonstrated increased expression of PDGF signaling components in C0 CHCHD2P9+ glioma cells, while SMCs exhibited high PDGFRB expression, suggesting a significant interaction between these cell types." (PMID 40630954, 2025). "This suggests that the PDGFRα or PDGFRβ pathway plays a role in cancer cell proliferation during the various stages of glioma development." (PMID 38473403, 2024). "INHEG activation enhances rRNA 2’-O-methylation, thereby increasing the expression of oncogenic proteins including EGFR, IGF1R, CDK6 and PDGFRB in glioma cells." (PMID 37980347, 2023). "Consistent with the reduced PDGFRβ levels upon SNX10 knockdown in GSCs, SNX10 expression correlated with a PDGFRβ signature score in glioma patients." (PMID 36795488, 2023). "PDGFRα is found to be expressed mostly in glioma cells, whereas PDGFRβ is expressed mainly by the stromal cells." (PMID 37790751, 2023). "Glioma cell-derived exosomes that have been loaded with PDGFRβ 9 siRNA via transfection suppress the proliferation of glioma cells by inhibiting the PI3K/Akt/EZH2 pathway." (PMID 37242707, 2023). "A study on glioma mouse model showed that M2-polarized microglia rather than M2-polarized bone marrow-derived macrophage is the reason for the elevated expression of PDGFRβ on glioma cells and their increased ability of migration." (PMID 37790751, 2023). "A high GPER1 level associated with a high expression of key genes involved in angiogenesis such as PDGFRB, which enhanced glioma cell migration and was proposed together with EGFR as a target for therapeutic agents." (PMID 36077653, 2022). "In support of this, PDGFD and PDGFRB were positively correlated with a three-gene signature (TGFBI, IGFBP3, and CHI3L1) associated with glioma tumor cell invasion and migration and poor patient survival." (PMID 34539622, 2021). "Another study showed that microglia can induce the expression of PDGFRB in glioma cells, thereby enhancing their migration ability." (PMID 34925244, 2021). "A PDGFR-β-specific shRNA can reduce viability and enhance GBM radiosensitivity, and silencing PDGFRB by RNAi was shown to enhance the radiosensitivity of C6 glioma cells in vivo." (PMID 34830952, 2021). "Many spots corresponding to mSIN staining colocalized with early endosomes identified by endocytosed PDGFRβ in U87MG glioma cells." (PMID 34065746, 2021). "Since PDGFD and PDGFRB were associated with genes involved in glioma tumor cell invasion and migration, we next examined the relationship between tumor expression of PDGFD or PDGFRB and LGG patient survival." (PMID 34539622, 2021). "PDGFRβ is expressed not only in vasculature, but also in GBM-associated stromal cells, which exert tumor-promoting effects on glioma cells in vitro and in vivo." (PMID 33193439, 2020).
glioma (continued). "To better define the phenotypic characteristics of FAP+ cells in human glioma samples, we first used FAP/nestin and FAP/PDGFRβ double immunostaining on human glioma specimens." (PMID 33308315, 2020). "Modification with Gint4.T increased the specificity and efficiency of TDN in glioma treatment by targeting the PDGFRβ that is expressed in large quantities on glioma cells." (PMID 32691170, 2020). "For example, the PDGFRβ-targeted aptamer chimera bearing the siRNA to STAT3 reduced glioma cell viability, tumor growth, and angiogenesis in a subcutaneous model of glioma." (PMID 30644073, 2019). "PDGFRB, platelet‐derived growth factor receptor beta, has some evidence linking DNA damage in gliomas and fibrosarcoma models (Medová, Aebersold, & Zimmer, 2013)." (PMID 31294536, 2019). "Similar results can be found in the mouse brain, where PDGFRβ is found to mediate the transition of vascular pericytes into glioma cells." (PMID 30902967, 2019). "Ten patients with PDGFRa overexpression and two patients with PDGFRb had a high-grade glioma, including GBM, anaplastic oligoastrocytoma, anaplastic oligodendroglioma and anaplastic pleomorphic xanthoastrocytoma (PXA)." (PMID 31882734, 2019). "Concomitantly, the mean EGFR, ERBB2, FGFR3, and PDGFRB mRNA levels were statistically lower than those of IDH-wildtype gliomas, which also exhibited a marked increase in EGFR and ERBB2 protein abundance." (PMID 27852048, 2017). "We observed increased DNA methylation in EGFR, ERBB2, ERBB3, FGFR3, and PDGFRB in IDH-mutant gliomas as the mean methylation of each gene was statistically greater than that of IDH-wildtype." (PMID 27852048, 2017). "We have utilized two independent pediatric high-grade glioma cell lines with either high platelet-derived growth factor receptor alpha (PDGFRα) or high PDGFRβ expression in in vitro assays to investigate the specific downstream effects of nilotinib treatment." (PMID 25732621, 2015). "We provide evidence of co-expression of CXCR4 and PDGFRβ in a human glioma cell line and in several primary glioblastoma specimen from patients." (PMID 24023874, 2013). "Glioma stem cells preferentially express PDGFRβ and its activation promotes glioma stem cell self-renewal, suggesting that targeting of this receptor can be beneficial in treatment of glioma patients." (PMID 24359404, 2013). "These PDGF-induced experimental gliomas are similar to human GBs in that the glial tumor cells express Pdgfrα whereas the vasculature expresses Pdgfrβ in pericytes." (PMID 21209724, 2011). "Overexpression of PDGFRβ has been demonstrated by in situ hybridization in the proliferative endothelium of gliomas." (PMID 27713269, 2010). "The overexpression of PDGF-B in glioma results in tumors with short latency, large area of necrosis, and angiogenesis, and PDGFRβ signaling is required for the maintenance of these characters." (PMID 27713269, 2010). "However, despite their reduced number, we observed PDGFRβ+ stromal cells outside tumor vessels interspaced with glioma cells, partially derived from type A pericytes." (PMID 34535655, 2021). "The PDGFRB inhibitor AG1433 induces cytotoxicity in high grade glioma cell lines." (PMID 34830952, 2021). "Although median expression level of PDGFRB is decreased relative to controls, there is a wide range of expression levels, which may also reflect distinct glioma subtypes." (PMID 20423517, 2010). "Progenitor or committed pericytes expressing the platelet-derived growth factor receptor-beta (PDGFR beta) may play a role in shaping the architecture of the vascular niche of an experimental model of glioma and promote endothelial cell survival through induction of autocrine VEGF signaling." (PMID 24069296, 2013). "We observed frequent ERK pathway reactivation in human glioma specimens following BRAF inhibitors, most commonly through EGFR and PDGFRβ activation." (PMID 40900823, 2025).
glioma (continued). "The correlation between CCL5 and the pericyte markers (Desmin (DES), platelet derived growth factor receptor beta (PDGFRB) or actin alpha 2 (ACTA2)) was confirmed in both the TCGA-GBM and the Chinese Glioma Genome Atlas (CGGA)-GBM datasets." (PMID 34239070, 2021). "In these “phospho-SFK high” tumours 66% also expressed high PDGFRA or PDGFRB or both, supporting a scenario in which PDGFR signalling contributes to SRC/SFK activation in high-grade gliomas." (PMID 33478100, 2021). "RTKs, including EGFR (epidermal growth factor receptor), PDGFRβ (platelet-derived growth factor receptor β), and FGFR (fibroblast growth factor receptor), are key therapeutic targets of glioma." (PMID 31794427, 2019). "By employing a co-immunoprecipitation (“Co-IP”) assay, we show that Ninj2 immunoprecipitated with EGFR, PDGFRβ and FGFR in A172 cells and primary human glioma cells (“P1/P2”)." (PMID 31794427, 2019). "The results of present study demonstrated that in glioma cells Ninj2 co-immunoprecipitated with multiple RTKs (including EGFR, PDGFRβ and FGFR), required for downstream Akt and Erk activation." (PMID 31794427, 2019). "In human glioma tissues and cells, Ninj2 co-immunoprecipitated with multiple receptor tyrosine kinases (EGFR, PDGFRβ and FGFR), required for downstream Akt and Erk activation." (PMID 31794427, 2019). "In the human glioma tissues (“T1/T2/T3”, derived three primary glioma patients), Ninj2-immunoprecipitation with EGFR, PDGFRβ and FGFR was detected as well." (PMID 31794427, 2019). "Since some gliomas express the PDGF-C receptors PDGFRα and PDGFRβ we checked for autocrine signaling in our U87MG cells." (PMID 19352490, 2009). "Another inhibitor of PDGFR⍺ and PDGFRβ is crenolanib (CP-868,596), which has demonstrated brain penetration as well as in vivo inhibition of PDGFR phosphorylation in murine models and in high grade glioma patients." (PMID 38615034, 2024). "M2-polarized microglia, rather than BMDMs, provoke PDGFRB expression in glioma cells and stimulate their migratory ability, and have a tight interaction with pericytes for intra-tumor angiogenesis." (PMID 37700840, 2023). "The number of PDGFRβ-positive pericytes and amount of collagen type IV (ColIV)-positive basement membrane (BM) were greatly decreased in GL261 glioma vessels but appeared to be maintained in EGFRVIII GBM vessels at levels equivalent to those in nontumor vessels." (PMID 36828931, 2023). "Inhibitors of PDGFRβ, EGFR, or SDF-1αR (DMPQ, gefitinib, and burixafor, respectively) significantly reduced the stimulatory effect of MCM in all cell lines, confirming the key role of microglia-derived PDGFβ, EGF, and SDF-1α in glioma cell migration." (PMID 34944779, 2021). "FAP+ cells were efficiently propagated in conditions suitable for pericytes, expressed mesenchymal markers PDGFRβ, αSMA, and TE-7, but were negative for glioma (GFAP) and endothelial (vWf) markers." (PMID 34282761, 2021). "Interestingly, expression of PDGFRA, a major growth factor receptor in glioma cells, was significantly reduced in GBM, whereas PDGFRB was increased." (PMID 34470658, 2021). "“INPUT” results confirmed Ninj2, EGFR, PDGFRβ and FGFR expression in the glioma tissues." (PMID 31794427, 2019). "“INPUT” results confirmed Ninj2, EGFR, PDGFRβ and FGFR expression in the glioma cells." (PMID 31794427, 2019). "Furthermore, OPCs and pericytes express PDGFRα and PDGFRβ, respectively, and it has been shown that PDGF is a strong inducer of glioma." (PMID 24465393, 2014). "In order to explore whether this contradiction exists in gliomas, we compared the expression levels of vascular stability-related markers (ANGPT1, ANGPT2, JAM2, MCAM, PDGFRB, and VE-Cadherin) in the high- and low-score glioma groups in the TCGA, CGGA, and CGGA (array) datasets." (PMID 35579998, 2022).
glioblastoma (107 papers, 2010 to 2025). The most malignant astrocytic tumor (WHO grade IV). "Further work demonstrated that SESN2 knockout impaired PDGFRβ degradation via reduced proteasomal activity, distinct from the mechanism observed in glioblastoma." (PMID 40361504, 2025). "There is evidence that VEGFRs are expressed at an increased level in glioblastoma cells and astrocytic tumor cells, and PDGFRb (tyrosine 75) is characterized by increased phosphorylation, compared to normal astrocytes." (PMID 36768736, 2023). "PDGFRA and PDGFRB exert a central function in the initiation and progression of many tumors, including glioblastoma, gastrointestinal stromal tumor, skin squamous cell carcinoma, and oral squamous cell carcinoma." (PMID 36421685, 2022). "For example, a Gint4.T Ap, specific for PDGFRβ (platelet-derived growth factor receptor beta) overexpressed on the glioblastoma cell line, U87MG, was integrated with PEG-PLGA NPs." (PMID 35159698, 2022). "As this radiotracer was able to visualize the expression of PDGFRβ in glioblastoma xenografts in a mice model, it would be promising in the context of NASH to study activated hepatic stellate cells in the liver." (PMID 34298967, 2021). "These glioblastoma stem cell-specific effects were accompanied by decreased phosphorylation of multiple proteins, including platelet-derived growth factor receptor beta (PDGFRβ), which was previously shown to be transactivated by D4 receptor stimulation." (PMID 28424758, 2017). "We analysed gene expression of the PDGF system (PDGFA, PDGFB, PDGFC, PDGFD, PDGFRA, PDGFRB) in 36 GBMs studied on Ivy Glioblastoma Atlas Project." (PMID 29127351, 2017). "We and others recently demonstrated that inhibition of either PDGFRα or PDGFRβ signaling induced apoptosis in glioblastoma stem cells." (PMID 27344175, 2016). "In this paper we demonstrated a functional cross talk between two receptors largely expressed in glioblastomas and playing key roles in tumor cell proliferation, infiltration and angiogenesis, PDGFRβ and CXCR4." (PMID 24023874, 2013). "Overall, the interaction between SESN2 and PDGFRβ in glioblastoma remains incompletely understood, and it is unclear whether PDGFRβ modulation by SESN2 significantly influences glioblastoma progression or reflects a broader regulatory mechanism." (PMID 40361504, 2025). "PDGFRβ is present in more than 90% of endothelial cells in glioblastoma samples." (PMID 40332381, 2025). "Therefore, the high expression of platelet-derived growth factor receptor β (PDGFRβ) in U87MG cells makes them a relevant model for studying targeted therapies at this receptor in glioblastoma." (PMID 38675202, 2024). "In disease states such as glioblastoma, tumor cells and platelet-derived growth factor receptor beta (PDGFRβ)-expressing cells of the neurovascular sub-units (such as pericytes and perivascular fibroblast-like cells) produce CCL2 to recruit regulatory T cells and dampen the effector response." (PMID 34771532, 2021). "Thus, a study evaluated the efficacy of an affibody molecule to monitor the expression of PDGFRβ in glioblastoma xenografts." (PMID 34298967, 2021). "Alternatively, inhibition of EGFR by erlotinib in EGFRvIII-expressing U87 glioblastoma cells may increase the expression of PDGFRβ, which compensates for signaling inhibited by erlotinib." (PMID 31284441, 2019). "Since PDGFRβ levels are increased in proneural glioblastoma, more robust D4 receptor co-activation may be particularly important in this subtype." (PMID 28424758, 2017). "In fact, it has been reported that EGFR-mutant glioblastomas may evade EGFR TKI by transcriptionally de-repressing PDGFRβ." (PMID 25380967, 2014). "Two of these (PDGFRB and EGFR) are implicated in glioblastoma." (PMID 20964819, 2010). "All prospective glioblastoma cases, including those driven by novel alterations, such as ST7–MET fusion or PDGFRB amplification, were successfully assigned to one of the subgroups." (PMID 38254850, 2024).
glioblastoma (continued). "Functionalized with two aptamers, GMT8, a short DNA sequence selected by SELEX, and Gint4.T, a 33 RNA oligonucleotide specific to PDGFRβ; this system aimed to target U87MG cells, a type of glioblastoma multiforme (GBM) cell line." (PMID 38675202, 2024). "A novel aptamer-siRNA chimera (Gint4.T-STAT3) was developed to deliver STAT3 siRNA efficiently and subsequently suppressed the expression of STAT3 in PDGFRβ+ glioblastoma multiforme (GBM) cells, through in vitro and in vivo studies, demonstrating that this is an effective strategy." (PMID 30847297, 2019). "Supporting PDGFRβ regulation by SNX10, a negative correlation between SNX10 expression and glioblastoma patient prognosis was observed in the proneural transcriptional subtype, which is characterized by elevated PDGFR signatures." (PMID 36795488, 2023). "Additionally, mutant EGFRvIII has been shown to suppress PDGFRβ expression via mTORC1- and ERK-dependent mechanisms and blocking such pathways de-repressed PDGFRβ signaling for growth and survival in glioblastomas." (PMID 30777101, 2019). "The final cell type common to all three specimens was characterised by expression of PDGFRB (PDGFRβ/CD140b), MCAM (CD146), THY1 (CD90), FN (fibronectin) and type IV collagen genes, markers typical of mature pericytes, including those in normal human brain and glioblastoma." (PMID 33082953, 2020).